PRNP (prion protein (Kanno blood group))
Diseases named in the same sentence as PRNP in open-access papers (continued):
Sharing a sentence is not in itself a finding about the gene and the disease.
prion disease (continued). "Totally 811 suspected cases have been referred to CCDC, among which 219 are diagnosed as sCJD, 30 are genetic prion diseases with PRNP sequencing confirmation." (PMID 23671608, 2013). "A rare stop codon mutation in the PRNP gene leads to the production of GPI-anchorless prion protein and the development of familial prion disease, which has been reproduced in mouse models." (PMID 23637596, 2013). "In some reports the protective effect of PRNP codon 129 heterozygosity is seen in some of the inherited prion diseases." (PMID 24324497, 2013). "Most of the human prion diseases are classified as CJD; approximately 85% of all cases of CJD occur sporadically, whereas 10-15% are caused by mutations in the prion protein gene (PRNP)." (PMID 25437206, 2013). "Transgenic mice expressing a PRNP gene from a species of interest are a suitable surrogate host for some studies of prion disease in humans, cattle, sheep and deer." (PMID 22472560, 2012). "Presence of single nucleotide polymorphisms (SNPs) in the intron of PRNP, retinoic acid receptor-β protein (RARB), and SCG10/stathmin-like 2, a neuronal growth-associated protein (STMN2) increased the risk of prion diseases." (PMID 23372423, 2012). "It has been well documented that besides PRNP, other genes are also involved in the pathogenesis of prion diseases." (PMID 23372423, 2012). "The study of the physiological functions of PRNP seems to be key to understanding both prion diseases and its possible implications in development and cancer biology." (PMID 21483752, 2011). "Overexpression of PRNP in transgenic mice led to a decrease in incubation time, whereas PRNP knockout mice were resistant to prion disease after infection." (PMID 19351416, 2009). "At PRNP codon 129, elderly Fore women survivors of the kuru epidemic showed a profound Hardy–Weinberg disequilibrium, with an excess of the prion disease-resistance genotype 129MV relative to both homozygous genotypes 129MM and 129VV." (PMID 19081515, 2009). "The three primary means of acquiring prion diseases are as follows: 1) infection – can be transmitted by the ingestion of meat obtained from diseased animals, 2) spontaneous – occurs sporadically via unknown mechanism(s) and 3) inherited – mutations in the PRNP gene encoding PrP." (PMID 18366654, 2008). "In this regard, it is important to consider whether prion diseases could potentially affect all animal species with a PRNP gene, or if there is a limited host range for prion propagation." (PMID 40561181, 2025). "Protein-coding variants in PRNP have been ruled out in all reported VPSPr patients, leading to classification of VPSPr as a sporadic, rather than genetic, prion disease." (PMID 39711705, 2025). "Therefore, this study was designed to understand the PRNP gene sequence variation in different Nigerian livestock species and provide insight into their resistance to prion diseases." (PMID 38355406, 2024). "This explains, for a large part, the sometimes-potent genetic modulation of prion disease susceptibility observed in scrapie and CWD, which is governed by alteration of the PRNP gene causing amino acid substitutions in the PrPC structure." (PMID 36832899, 2023). "In the present study, in line with recently proposed prognostic models, we carried out the survival analyses also considering clinical variables known to have a prognostic role in prion diseases such as age at LP, PRNP codon 129 genotype, and time between symptoms onset and LP." (PMID 37684653, 2023). "Third, differences in risk of prion disease by sex, age, and codon 129 genotype do not appear to be explained by different levels of PRNP expression." (PMID 35585119, 2022). "The early presentation of frontotemporal symptoms and typical imaging changes related to FTD in PRNP mutation carriers, as well as the lack of typical symptoms or ancillary findings related to prion diseases, increases the risk of misdiagnosis." (PMID 35768878, 2022).
prion disease (continued). "In addition to playing a key role in genetic prion diseases, variations in PRNP sequences are also important for sporadic and acquired prion diseases." (PMID 36277922, 2022). "As there may be phenotypical similarities between prion diseases and other diseases, including PRNP, in gene panel studies, it is essential." (PMID 36614069, 2022). "Carriers of PRNP mutations phenotyped as FTD usually have a longer disease course and higher portion of codon 129 Val genotype, and lack the typical clinical and ancillary features of prion diseases." (PMID 35768878, 2022). "Prion diseases can be caused by the spontaneous conversion of PrPC into PrPSc (as proposed for sCJD) or by somatic mutations in the PRNP gene in familial forms of CJD, which render PrPC susceptible to misfolding and aggregation." (PMID 35416570, 2022). "Genetic prion diseases like genetic Creutzfeldt–Jakob disease (gCJD), fatal familial insomnia (FFI) and Gerstmann–Straussler–Scheinker syndrome (GSS) account for 5% of cases and are all caused by mutations in the PRNP gene." (PMID 33450819, 2021). "In inherited prion diseases (IPD), it results from mutation of the prion protein gene (PRNP)." (PMID 33674752, 2021). "Prion diseases typically manifest a wide range of phenotypic variability, depending on genetic factors, namely, the primary sequence of the prion protein gene (PRNP), and PrPSc intrinsic properties likely related to the conformational heterogeneity of PrPSc multimers." (PMID 34324063, 2021). "Therefore, definite diagnosis of TSE ante-mortem is not achievable by these means, with the exception of genetic prion diseases in which sequencing of PRNP gene can certainly support a clinical manifestation-based diagnosis." (PMID 32204429, 2020). "Focusing on the genetic aspects, the identification of specific mutations in the PRNP gene causing rare genetic forms of prion diseases such as the Gerstmann-Sträussler-Scheinker disease and FFI heralded the identification of PRNP mutations in familial forms of CJD." (PMID 32151109, 2020). "Like other prion diseases, CWD susceptibility is partly dependent on the sequence of the prion protein encoded by the host’s PRNP gene; it is unknown if variations in PRNP have any meaningful effects on other aspects of health." (PMID 32033521, 2020). "Combined with the reported lack of such antibodies in carriers of disease‐associated PRNP mutations, this suggests a link to the low incidence of spontaneous prion diseases in human populations." (PMID 32776637, 2020). "In one study, serum samples were analysed from 128 individuals with various pathogenic prion disease-associated PRNP mutation and 78 control individuals that lacked these mutations but had a positive family history of genetic prion disease." (PMID 33023255, 2020). "Variation in PRNP (the gene encoding PrPC), particularly within the open reading frame (ORF), is associated with the occurrence of prion disease and may affect prion strain characteristics." (PMID 31852336, 2020). "Prion diseases can present with a wide spectrum of phenotypes, for several reasons, including importantly, variation of the coding sequence of the prion protein gene (PRNP) and the propagation of prion strains." (PMID 31734530, 2019). "Besides supporting the role of PrPsc as an infectious agent of prion disease, PRNP knockout (KO) experimental models have provided some insights into the physiological function of PrPc." (PMID 31618844, 2019). "This hypothesis is supported by the finding of the dysregulation of PRNP gene, which is down-regulated in nearly all prion diseases analyzed, and again with particular relevance in iCJD samples." (PMID 29142239, 2017). "Recent work in a mouse model of E200K prion disease in which transgenic mice (carrying chimeric human/mouse PRNP) develop neurological disease and accumulate PrPSc suggests that oxidative stress synergistically interacts with the E200K mutation to induce disease." (PMID 29262866, 2017).
prion disease (continued). "Family histories and PRNP sequencing results of various human genetic prion diseases." (PMID 26488179, 2015). "Our results demonstrate that the links between PRNP genotype and clinical prion disease in sheep are much less secure than previously thought, and may break down when, for example, a different breed of sheep is moved into a new flock." (PMID 26587837, 2015). "In addition, other PrPSc fragment sizes have been noted in association with other human prion diseases, e.g. GSS with the P102L mutation in PRNP, in which either type 1 PrPres or a low molecular mass ~8 kDa PrPres fragment can predominate." (PMID 25331173, 2014). "In general, these genetic forms show incomplete or age-dependent penetrance, as frequently family members carrying a PRNP mutation do not develop prion diseases." (PMID 23966072, 2013). "A genome-wide study in patients with various forms of prion diseases (variant, sporadic, iatrogenic CJD and kuru patients) confirmed that the risk of developing prion diseases is strongly associated with the polymorphic codon 129 of the PRNP gene." (PMID 23372423, 2012). "In addition to the obvious importance of the PRNP gene in modulating prion diseases, there are clinical and experimental findings that demonstrate that other factors play a role in disease pathogenesis." (PMID 19657386, 2009). "The ability of [SP14+] prion to interconvert between variants rapidly may provide an avenue to investigate the mechanisms underlying the high degree of phenotypic heterogeneity observed with prion diseases that arise due to repeat expansions in PRNP." (PMID 18366654, 2008). "Inherited prion diseases (IPDs) are a phenotypically diverse group of neurodegenerative diseases caused by mutations in the prion protein gene, PRNP, which are not always straightforward to identify clinically and can mimic other gradually progressive neurodegenerative diseases." (PMID 40156621, 2025). "All in all, our PRNP gene-based tree, despite showing some topological differences with the reference species tree that could be in some cases related to prion disease susceptibility, is not significantly distinct." (PMID 40561181, 2025). "Therefore, it is recommended to screen for the PRNP mutations in the patients with genetically undefined FTD, especially those with early age of onset, positive family history, and presenting typical clinical features of prion diseases and seizures." (PMID 35768878, 2022). "However, similar reports of extended incubation periods in PRNP codon 129 heterozygous individuals have been described in other acquired forms of human prion disease involving oral and peripheral routes of exposure—specifically, kuru and human growth hormone associated iCJD cases in France." (PMID 34832569, 2021). "In addition, genetic sequencing on eight of the 10 cases found no mutations in the prion protein gene (PRNP) that is associated with the inherited forms of prion disease." (PMID 34832569, 2021). "Similarly, PrP autoantibody titers present in a subset of PRNP mutation carriers neither correlated with the PRNP mutation status nor with the onset of clinical prion disease." (PMID 32776637, 2020). "Although the accumulation of hyperphosphorylated Tau in the cerebral cortex is not a general feature of human prion disease neuropathology, it has been found in human cases and experimental mouse models of vCJD as well as in patients with a specific PRNP point mutation causing GSS." (PMID 26630676, 2015). "However, a recent systemic review concluded that the I203 mutation of the PRNP gene did not exhibit high penetrance and could be benign or is only associated with susceptibility to prion disease." (PMID 37834279, 2023). "We found out that the amyloid formation of PRNP in two of the haplotypes (HYKK and HDKK) was similar to the resistance haplotype (HYNN) to prion diseases in this study." (PMID 36892181, 2023).
prion disease (continued). "Recently, 48 somatic mutations in PRNP were identified in cancer patients, among which 8 were reported to be pathogenic for prion diseases, and that cancer patients carrying mutations of PRNP may produce PrPSc and may not be diagnosed with prion disease." (PMID 37452879, 2023). "A total of 136 cases of prion diseases, including 119 cases of probable sporadic CJD, 4 of gCJD (PRNP T188K), 11 of FFI (D178N/129MM), and 2 of GSS (PRNP P102L) were enrolled in this study." (PMID 35768878, 2022). "Humanized transgenic mouse brain (TgHu) expressing the three polymorphic genotypes of PRNP codon 129 (TgHuMM, TgHuMV, TgHuVV) have been commonly used as a PMCA substrate to examine the zoonotic threat posed by animal prion diseases." (PMID 34413769, 2021). "Although there is no equivalent polymorphism to L141F in the human PRNP gene, the PRNP M129V polymorphism is associated with variation in the incubation period of acquired human prion diseases, and therefore may have similar effects on transmission of vCJD by transfusion." (PMID 33600501, 2021). "Because of the close genomic location and similar structure to PRNP, PRND has been noted as another major candidate gene in prion diseases." (PMID 30359416, 2018). "In our cohort, presence of protein 14-3-3 positivity and isolated T-tau CSF values were significantly higher in prion diseases than in other neurodegenerative diseases, regardless of whether the prion disease had a sporadic or genetic origin and regardless of codon 129 PRNP polymorphisms." (PMID 25886404, 2015). "PRNP genotyping should be considered for patients with FTD phenotype exhibiting early-onset, family history of the disease and presenting clinical features of prion disease." (PMID 35768878, 2022). "In this study, we found that the absence of SNPs in the chicken PRNP ORF is a notable feature of animals with perfect resistant to prion disease." (PMID 31795947, 2019). "In the context of prion disease, SFV DNA, RNA and recombinant particles were employed for the expression of prion protein (PRNP), which allowed generation of monoclonal antibodies against PRNP in immunized mice." (PMID 27827980, 2016). "For several types of prion disease, however, no effective rPrPSen substrate has been identified; these types include human GSS arising from P102L*, F198S, A117V and H187R PRNP mutations and the atypical sheep scrapie strain Nor98." (PMID 26086786, 2015). "Based upon the patient’s history of a severely progressive neurological disorder with basal-ganglia symptoms/signs, ataxia and a major antecedent psychiatric presentation, diagnoses of either WD or genetic prion disease were considered, and DNA sequence analysis of ATP7B and PRNP was requested." (PMID 24555712, 2014). "Despite clear evidence from mouse linkage studies of multiple genetic loci affecting incubation periods of prion diseases, no specific human genes have been identified, apart from the prion protein gene (PRNP)." (PMID 18805828, 2008). "In similarity with previous studies looking at PRNP mutations E200K and Y218N (responsible for cases of hereditary CJD and GSS respectively) in human neuronal tissue backgrounds, the mutation did not spontaneously cause prion disease." (PMID 36656833, 2023). "The clinical symptoms and disease duration also differed, and based on analyses of the PRNP gene, genetic prion disease could be ruled out, rendering the newly discovered disease a “new variant” of CJD." (PMID 36832899, 2023). "Thus, the genetic characteristic of the absence of SNPs in the chicken PRNP gene is a notable features of prion disease-resistant animals." (PMID 31795947, 2019). "Although no case of prion disease has been reported in a free-ranging individual of any species within this superfamily, mink develop TME in captivity and must therefore be regarded as carrying a susceptible PRNP genotype." (PMID 23236380, 2012).
prion disease (continued). "Aiming to advance our understanding of the molecular pathogenesis of human prion diseases, we used the conformation-dependent immunoassay (CDI) to determine the conformational range and strain-dependent molecular features of sCJD PrPSc in patients who were homozygous for codon 129 of the PRNP gene." (PMID 21931554, 2011).